RNU1-100P (RNA, U1 small nuclear 100, pseudogene)
Gene: Small nuclear RNA gene on chromosome 3 (142,420,205 to 142,420,369, reverse strand). Ensembl gene ENSG00000202125.
Homologues: Orthologues: chimpanzee U1 (98% identical), macaque U1 (93% identical), rabbit U1 (73% identical). Paralogues in human: RNU1-1 (85% identical), RNU1-2 (85% identical), RNU1-27P (85% identical), RNU1-28P (85% identical), RNU1-3 (85% identical), RNU1-4 (85% identical), RNVU1-18 (85% identical), RNVU1-29 (85% identical), U1 (85% identical), RNU1-83P (84% identical), RNU1-89P (84% identical), RNVU1-28 (84% identical), and 134 more.